UCA1-AS1 (UCA1 antisense RNA 1)
Synonyms: CLEC4O; LINC01835; CLEC4OP; formerly LINC01764
Gene: Long non-coding RNA gene on chromosome 19 (15,821,851 to 15,865,032, reverse strand). Ensembl gene ENSG00000267308.
Diseases named in the same sentence as UCA1-AS1 in open-access papers:
UCA1-AS1 is named in the same sentence as 4 diseases in open-access papers, as found by Europe PMC text mining. Sharing a sentence is not in itself a finding about the gene and the disease.
UCA1-AS1 shares sentences with these, for which no sentence is quoted: colorectal cancer (2 papers); bladder cancer (1); cancer (1); tumor (1).